GSDMA (gasdermin A)
Diseases named in the same sentence as GSDMA in open-access papers (continued):
Sharing a sentence is not in itself a finding about the gene and the disease.
gastric cancer (continued). "Additionally, GSDMA expression was frequently suppressed in esophageal cancer cell lines and gastric cancer cell lines, whereas GSDMB was expressed in all investigated cancer cell lines and also showed evidence of gene amplification and overexpression in some cases of gastric cancer." (PMID 26484354, 2015). "Gasdermin A (GSDMA) is the least investigated member and is expressed in epithelial cells of the gastric tract while suppressed in gastric cancer." (PMID 35626754, 2022). "In addition to GSDMA, GSDMB, and GSDMC, GSDMD reportedly inhibited proliferation of the gastric cancer cell line MKN28 in a colony formation assay." (PMID 34858408, 2021).
breast cancer (10 papers, 2015 to 2025). A primary or metastatic malignant neoplasm involving the breast. "Since there have been only a few studies on GSDMA in breast cancer, further studies are needed for a deeper understanding of the role of GSDMA in breast cancer." (PMID 36823153, 2023). "Specifically, Sahlberg and colleagues proved that silencing either STARD3, GRB7, PSMD3, PERLD1, PPP1R1B, THRA, or GSDMA partially sensitized specific breast cancer cell lines to anti-HER2 agents." (PMID 36139701, 2022). "A previous study found that GSDMA expression may increase the sensitivity of breast cancer cells against PD-L1 immunotherapy." (PMID 37859811, 2023). "Analysis of data from the Kaplan-Meier Plotter database revealed that higher GSDMA expression was related to better survival in BLCA and breast cancer." (PMID 36003332, 2022). "The two immediate proximal genes instead, LRRC3C and GSDMA, neither interact with the mutation site nor expressed at detectable levels in either the MCF-7 breast cancer cell line or primary breast tumors (TCGA)." (PMID 30404658, 2018). "GSDMB is a member of the gasdermin (GSDM) family that consists of four genes, GSDMA, GSDMB, GSDMC and GSDMD, and is expressed in proliferating cells of normal epithelium and also in many types of cancer, including esophageal, gastric, liver, colon, uterine cervix and breast cancers." (PMID 26016667, 2015). "However, treatment with 5-aza-2’-deoxycytidine (5-aza-dC), a DNA methyltransferase inhibitor, could upregulate the expression of GSDMA but not GSDMB in the MCF7 cell, indicating that GSDMA expression is mediated by DNA methylation in breast cancer." (PMID 36823153, 2023). "Although GSDMA and GSDMB are located at the same human chromosomal region (17q21), unlike GSDMA, GSDMB is markedly over-expressed in breast cancer and acts as an oncogene." (PMID 36823153, 2023).
systemic sclerosis (8 papers, 2017 to 2024). A chronic disorder, possibly autoimmune, marked by excessive production of collagen which results in hardening and thickening of body tissues. "But GSDMA polymorphism was associated with childhood asthma, inflammatory bowel disease and systemic sclerosis." (PMID 35211500, 2022). "The results of transethnic meta-analysis of genome-wide associated studies involving Japanese and European populations with a total of 4,436 cases and 14,751 controls revealed that a missense mutation in GSDMA (rs3894194) is associated with system sclerosis." (PMID 34858408, 2021). "SNPs of GSDMA are associated with systemic sclerosis (SSc), inflammatory bowel disease (IBD), and childhood asthma." (PMID 37771587, 2023). "Whether GSDMA is cleaved by other microbial or host cell proteases, and if GSDMA variants linked to autoimmune diseases with skin pathologies, such as systemic sclerosis, alter GSDMA activity, will be of significant interest to determine." (PMID 35608339, 2022).
inflammatory bowel disease (7 papers, 2015 to 2024). A spectrum of small and large bowel inflammatory diseases of unknown etiology. "GSDMA mutants have been linked to limited cutaneous system sclerosis and inflammatory bowel disease." (PMID 34858408, 2021). "GSDMA has been associated with immune-related diseases, such as asthma, inflammatory bowel disease (IBD) and limited cutaneous systemic sclerosis (lcSSc)." (PMID 33634141, 2021). "In contrast to GSDMA, reduced expression of GSDMB increased the susceptibility to inflammatory bowel disease." (PMID 34858408, 2021).
ovarian carcinoma (5 papers, 2022 to 2023). A malignant neoplasm originating from the surface ovarian epithelium. "Conversely, GSDMA is overexpressed in ovarian cancer tissues compared to normal tissues and is associated with a poorer prognosis." (PMID 38066523, 2023). "provided a novel gene signature including 7 PRGs (AIM2, PLCG1, ELANE, PJVK, CASP3, CASP6, and GSDMA) for predicting the prognosis of ovarian cancer (OC) patients and laid a foundation for further studies of the relationships between PRGs and immunity in OC." (PMID 35912258, 2022). "Hence, GSDMA serves as a protumorigenic factor in ovarian cancer." (PMID 38066523, 2023). "At present, studies have shown that GSDMD 7, 33 and GSDME 32, 33 are the key targets that cause pyroptosis in ovarian cancer cells, while GSDMA and GSDMC have not been proven to be involved in the pyroptosis of ovarian cancer cells, which is consistent with our analysis results." (PMID 37859811, 2023). "In the gasdermin family, GSDMA (logFC=1.38557, FDR=5.23e-15) and GSDMC (LogFC=2.298323, FDR=2.06e-38) was significantly overexpressed in ovarian cancer, while the expression of GSDMD (logFC=-1.10275, FDR=8.25e-30) and GSDME (logFC=-2.29572, FDR=1.54e- 46) was significantly lower in ovarian cancer." (PMID 37859811, 2023).
autoimmune disease (4 papers, 2017 to 2024). A disorder resulting from loss of function or tissue destruction of an organ or multiple organs, arising from humoral or cellular immune responses of the individual to their own tissue constituents. "This study reveals how SVV subverts host inflammatory defense by disrupting GSDMA-induced pyroptosis, thereby advancing our understanding of antiviral immunity and opening avenues for treating GSDMA-associated autoimmune diseases." (PMID 39207099, 2024).
childhood asthma (4 papers, 2011 to 2023). "Previous studies have reported that the 17q21 locus alleles in genes GSDMA, GSDMB, IKZF3, ZPBP2, and ORMDL3 are associated with increased risk and severity of childhood asthma and increased number of early wheezing illnesses." (PMID 36967681, 2023). "Variants in the ORM1-like 3 (ORMDL3) gene and in neighbouring genes, such as gasdermin A and B (GSDM), have consistently been associated with risk of childhood asthma." (PMID 22350146, 2012). "Our GWAS dataset supported an association between identical SNPs reported in ORMDL3/GSDMB/GSDMA, IL5/RAD50/IL13, HLA-DR/DQ, and SMAD3 and pediatric asthma (P<0.05)." (PMID 21814517, 2011).
deafness (4 papers, 2022 to 2024). An inherited or acquired condition characterized by the complete loss of the ability to hear from one or both ears. "Six types of GSDMs paralogous genes, namely GSDMA, GSDMB, GSDMC, GSDMD, and GSDME [also termed deafness, autosomal dominant 53 (DFNA5)], and pejvakin [PJVK; also termed deafness, autosomal recessive 59 9DFNB59)], have been found in humans." (PMID 36003332, 2022). "Gasdermin A (GSDMA), GSDMB, GSDMC, GSDMD, GSDME (also known as deafness, autosomal dominant 5, DFNA5), and DFNB59 are the six GSDMs that have been identified in humans." (PMID 35359964, 2022).
glioma (4 papers, 2021 to 2025). A benign or malignant brain and spinal cord tumor that arises from glial cells (astrocytes, oligodendrocytes, ependymal cells). "Overexpression of GSDMA is associated with glioma immune escape and poor prognosis in patients, while GSDMA knockdown increases T cell antitumor response via immunotherapy." (PMID 40236694, 2025).
Sepsis (4 papers, 2022 to 2023). Sepsis is defined as life-threatening organ dysfunction caused by a dysregulated host response to infection. "Among them, four classes are implicated in sepsis, including GSDMA, GSDMB, GSDMD and GSDME, with GSDMD being the most widely studied." (PMID 38022612, 2023). "GSDMA has been poorly studied in sepsis, and GSDMA in sepsis needs further exploration." (PMID 38022612, 2023). "Notably, during sepsis, the protein expression of GSDMA-NT, GSDMD-NT and GSDME-NT are reported to increase in sepsis-associated organ injuries, indicating that pyroptosis could play important roles in sepsis." (PMID 35967871, 2022).
colorectal cancer (3 papers, 2019 to 2026). A primary or metastatic malignant neoplasm that affects the colon or rectum. "Though our analysis, we found that GSDMA, GSDMB, GSDMD and GSDME might be involved in colorectal cancer cell invasion and metastasis, and the former three might played as negative regulators while the last one played as a positive regulator." (PMID 35164740, 2022). "In colorectal cancer, GSDME might be a positive regulator in cell invasion and metastasis through cell migration and angiogenesis, while GSDMA, GSDMB and GSDMD might be a negatively regulator of cell migration." (PMID 35164740, 2022). "Interestingly, in colorectal cancer cell lines, we found the genes positively correlated with GSDMA had no intersection (none gene) with the genes negatively correlated with GSDMB, but it had intersection (1022 genes) with the genes positively correlated with GSDMB." (PMID 35164740, 2022).
hepatic carcinoma (3 papers, 2021 to 2025). "Additionally, GSDMA, GSDMC and PJVK were lowly expressed in hepatic carcinoma cells, especially GSDMA." (PMID 39816682, 2025).
skin infection (3 papers, 2022 to 2024). An inflammatory process affecting the skin, caused by bacteria, viruses, parasites, or fungi. "Human and mouse GSDMA are cleaved by a bacterial cysteine protease called SpeB that is secreted by group A Streptococci during invasive skin infection." (PMID 38497531, 2024). "Given the skin-site expression of GSDMA in relation to Streptococcus infection, this group decided to focus on GSDMA and observed GSDMA can defend against Streptococcus mediated skin infections in mice through SpeB-driven GSDMA-mediated keratinocyte pyroptosis." (PMID 37266429, 2023). "As clearly shown in GSDMA-deficient mice infected with SpeB-producing GAS, this cleavage event is key to preventing the systemic spread and fatal course of GAS following local skin infection." (PMID 35414713, 2022). "Similar to GSDMD, GSDMA is expressed at high levels in keratinocytes; however, its potential contribution to pyroptosis and antibacterial immunity during GAS skin infection remains unclear and is the subject of the study highlighted here." (PMID 35414713, 2022).
alopecia (2 papers, 2023 to 2024). Hair loss usually from the scalp. "Mutations of human GSDMA, GSDMC, GSDMD, and GSDME in the region of GSDM-CT, where mutations induce alopecia in mice, also cause their activation and pyroptosis." (PMID 37771587, 2023).
Crohn disease (2 papers, 2015 to 2026). A gastrointestinal disorder characterized by chronic inflammation involving all layers of the intestinal wall, noncaseating granulomas affecting the intestinal wall and regional lymph nodes, and transmural fibrosis. "Higher GSDMA expression in naïve/central‐memory CD4+ T cells was protective in UC and Crohn disease, whereas up‐regulation in cytotoxic CD8+/natural‐killer cells increased the risk for hidradenitis suppurativa and ankylosing spondylitis." (PMID 41442179, 2026).
adrenocortical carcinoma (1 paper, 2022). "GSDMA showed significant differences in mRNA expression between different clinical stages of four cancers, namely adrenocortical carcinoma (ACC), HNSC, testicular germ cell tumors (TGCT), and THCA." (PMID 36003332, 2022).
airway hyperresponsiveness (1 paper, 2015). "GSDMA has also been linked with airway hyperresponsiveness in genetic association studies." (PMID 26100518, 2015).
colorectal tumors (1 paper, 2025). "We found that the transcriptional levels of GSDMA, GSDMC, and PJVK were significantly increased in human colorectal tumors; while, the expression of GSDMB, GSDMD, and GSDME remained unchanged." (PMID 40213993, 2025).
cutaneous melanoma (1 paper, 2022). A primary melanoma arising from atypical melanocytes in the skin. "GSDMA mutation was more likely associated with intrahepatic cholangiocarcinoma, uterine mixed endometrial carcinoma and cutaneous melanoma." (PMID 35164740, 2022). "Intrahepatic cholangiocarcinoma, cutaneous melanoma, uterine endometrioid carcinoma and uterine mixed endometrial carcinoma had the highest GSDMA (6.67%), GSDMB (2.7%), GSDME (6.52%) and PJVK (4.76%) mutation frequency, respectively." (PMID 35164740, 2022).
diabetic cardiomyopathy (1 paper, 2023). Diabetic cardiomyopathy is a disorder of the heart muscle in people with diabetes. "Silencing of circ_0071269 was shown to attenuate cardiac dysfunction in mice with diabetic cardiomyopathy, by sponging miR-145 and thereby upregulating Gasdermin A (GSDMA), an important regulator of pyroptosis." (PMID 38259314, 2023).
epidermoid carcinoma (1 paper, 2025). "Similarly, in human epidermoid carcinoma A431 cells infected with Group A Streptococcus (GAS), the bacterial protease SpeB directly cleaves GSDMA, releasing its GSDMA-NT, which initiates pyroptotic cell death." (PMID 40978461, 2025).
esophageal adenocarcinoma (1 paper, 2022). A malignant tumor with glandular differentiation arising predominantly from Barrett mucosa in the lower third of the esophagus. "Esophageal adenocarcinoma had the highest frequency of GSDMA (20.69%) and GSDMB (21.84%) amplification." (PMID 35164740, 2022).
osteosarcoma (1 paper, 2022). A usually aggressive malignant bone-forming mesenchymal neoplasm, predominantly affecting adolescents and young adults. "Through the survival analysis of the single gene, the BAK1, CASP6, and GSDMA were found to be linked to the prognosis of osteosarcoma." (PMID 36244998, 2022). "The expression level of CHMP4C was found to positively correlate with the risk score, while GSDMA was found to negatively correlate with the high risk of osteosarcoma, suggesting that CHMP4C may be a risk factor." (PMID 36244998, 2022). "By the Lasso Cox regression analysis, 6 key PRGs were screened for constructing the optimal model, namely CHMP4C, GZMA, BAK1, CASP1, CASP6, and GSDMA, and a six PRGs signature was successfully constructed for osteosarcoma." (PMID 36244998, 2022).
pneumonia (1 paper, 2022). An acute, acute and chronic, or chronic inflammation focally or diffusely affecting the lung parenchyma, caused by an infection in one or both of the lungs (by bacteria, viruses, fungi, or mycoplasma.). "Upregulated GSDMA levels in patient with SSc may lead to pneumonia caused by Streptococcus pyogenes or other toxins." (PMID 35962439, 2022).
psoriasis (1 paper, 2022). An autoimmune condition characterized by red, well-delineated plaques with silvery scales that are usually on the extensor surfaces and scalp. "In contrast, psoriasis skin-derived S.B cells expressed high levels of pyroptosis-related genes, such as CASP1, CAPS8, GSDMA, GSDMB, and GSDMD." (PMID 35962439, 2022). "Interestingly, compared with psoriasis skin-derived S.C cells, control skin cells highly expressed pyroptosis-related genes (CASP4, GSDMA, and GSDMC), suggesting that psoriasis skin-derived S.C cells were not sensitive to pyroptosis." (PMID 35962439, 2022).
rheumatoid arthritis (1 paper, 2026). A chronic, systemic autoimmune disorder characterized by inflammation in the synovial membranes and articular surfaces. "This integration across CD4+ naïve/central‐memory, CD8+ effector‐memory, CD8+ naïve/central‐memory, and natural killer cells identified HS as having a consistent risk direction for GSDMA, and rheumatoid arthritis as having an overall protective direction." (PMID 41442179, 2026).
ulcerative colitis (1 paper, 2023). An inflammatory bowel disease involving the mucosal surface of the large intestine and rectum. "Before the pore-forming function of gasdermins was discovered, and similar to GSDMA, GSDMB was genetically linked to asthma, ulcerative colitis, Crohn’s disease, and rheumatoid arthritis." (PMID 37266429, 2023).
viral infection (1 paper, 2022). "Thus, future studies that evaluate additional mutant HSV-1 strains could unmask a possible role for caspase-14 and GSDMA during viral infection." (PMID 36146839, 2022).